AR (androgen receptor)
Diseases named in the same sentence as AR in open-access papers (continued):
Sharing a sentence is not in itself a finding about the gene and the disease.
tumor (continued). "Multivariate analysis revealed interaction between LN status and AR-DIA (p < 0.001) as the strongest prognostic factor, followed by fibrotic focus (FF; p = 0.009), mitotic activity index (MAI; p = 0.018), and stromal tumor-infiltrating lymphocytes (sTILs; p = 0.041)." (PMID 39851328, 2025). "Similarly, the androgen receptor (AR) plays a critical role in BC, particularly in TNBC, where AR signaling can drive tumor progression." (PMID 41011238, 2025). "Tumour growth is usually dependent upon the androgen receptor (AR) pathway and hence therapies for non-organ-confined disease target this signalling axis." (PMID 40641632, 2025). "In post-ADT relapse samples, two cases showed strong AR staining in nearly all tumor cells, one had approximately 40% AR-positive cells, and two were completely negative for AR expression." (PMID 41213907, 2025). "Targeting transcription factors (e.g., STAT3, AR, and Nrf2) or epigenetic regulators (e.g., EZH2 and PRMT) could facilitate a strategy that induces ferroptosis while simultaneously inhibiting tumor-promoting immunity." (PMID 41438466, 2025). "In addition to directly killing AR-positive cancer cells via apoptosis and prolonging the doubling time by actively dividing cells into a quiescent state, ADT influences tumor angiogenesis." (PMID 40625920, 2025). "As previously seen, AR staining was prominent in the nuclei of metastatic tumor epithelial cells, while most stromal cells were AR-negative." (PMID 40841830, 2025). "In androgen receptor-negative (AR-) human prostate cancer cell xenografts implanted in the flank regions of mice, oral administration of resveratrol led to reduced tumor volume, decreased tumor cell proliferation, and promoted apoptosis." (PMID 41304967, 2025). "Notably, overexpression of the miRNA signature downregulated the Androgen Receptor (AR) expression via WT1 and FOXA1 repression, impaired the tumor-sphere forming ability of cells and was able to reverse cancer stemness." (PMID 40399259, 2025). "Mechanistically, the tumor suppressors ING1b and ING2 mediate AR-induced hTERT repression as corepressors supporting the notion that SAL has tumor suppressive activity." (PMID 41264145, 2025). "Additionally, AR activity in T cells can lead to reduced IFN-γ production and resistance to tumor immunotherapy, diminishing the effectiveness of immune checkpoint inhibitors (ICIs)." (PMID 40303343, 2025). "AR+/TREM2+/SPP1+ TAM fraction; TAM–tumor proximity scores; APOE–TREM2 pathway activity." (PMID 41488638, 2025). "However, approximately one-third of metastatic castration-resistant PCa (mCRPC) lesions may exhibit low or absent PSMA expression due to tumor heterogeneity, prior androgen deprivation therapy, or loss of androgen receptor expression, subsequently altering their response to PSMA-targeted therapy." (PMID 41226028, 2025). "The introduction of androgen receptor (AR)-targeting agents, such as abiraterone acetate, has significantly improved survival in patients with CRPC by inhibiting androgen biosynthesis from the adrenal glands, testes, and tumor cells." (PMID 41446858, 2025). "Notably, CRPC-associated iCAFs may reshape the local AR signaling milieu via steroid metabolism–related enzymes (e.g., HSD17B2) while secreting pro-migratory and pro-invasive factors (e.g., ITGBL1), thereby promoting tumor cell invasiveness and a castration-resistant phenotype." (PMID 41514658, 2025). "Although our findings support the crucial role of C/EBPβ in tumor aggressiveness in AR-TNBC, we did not evaluate the role of different C/EBPβ isoforms or the LIP-to-LAP ratio in tumor characteristics." (PMID 40448099, 2025). "In addition to the inherent resistance of the PSA−/low AR−/low cell subset to chemotherapy drugs and androgen signaling inhibitors, drug treatment inhibits AR signaling, thereby resulting in the acquisition of a PCSC phenotype by tumor cells." (PMID 39711287, 2025).
tumor (continued). "In preclinical models, systemic p300/CBP degradation inhibited tumor growth, synergized with AR antagonists and showed no evident toxicity." (PMID 41044247, 2025). "Collectively, the results presented in these prior studies (i.e., molecular mechanisms promoting AR activity in HER2-high tumor cells) reflect years of prolonged ADT for recurrent PCa, such that the therapeutic window for cotargeting HER2 and AR would have been lost." (PMID 40906535, 2025). "Additionally, in tumor cells there is a correlation between PSA failure and cytoplasmic FAM111A (p=0.0406), nuclear AR and pathological stage (p=0.0302), and a trend between PSA failure and pathological stage (p=0.065)." (PMID 40446667, 2025). "While in neutrophils, AR activation stimulates pro-inflammatory cytokines, such as TNF-α, by regulating promoter activity, in macrophages, it controls their polarization and differentiation toward the pro-tumor M2 phenotype." (PMID 40940929, 2025). "We demonstrated that PlexinD1 is transcriptionally suppressed by AR via direct AR interaction with PLXND1 promoter, which is a likely mechanism for the upregulation of PlexinD1 observed in PCa tumor clinical samples post-hormone therapy as well as in AR-negative CRPC and NEPC cells." (PMID 39748059, 2025). "Additionally, an analysis of tumor tissue from a PCa tissue array disclosed an inverse correlation between APOE and AR protein expression." (PMID 40365288, 2025). "PROX1 was also highly expressed in a separate NEPC tumor cell population that was AR and KLK3 negative but positive for NEPC markers, including INSM1." (PMID 40454483, 2025). "JARID1D is capable of demethylating H3K4me3 marks to inhibit tumor invasion 15; however, whether the affinity between JARID1D and AR regulates the level of H3K4me3 in the AR promoter region needs further investigation." (PMID 39816691, 2025). "Bioinformatics prediction and literature evidence suggest the tumor suppressive functions of LINC01133 may occur through sponging miR-205-5p to derepress the miR-205-5p targets LRRK2 and AR." (PMID 39744510, 2025). "Mechanistically, tumor-derived exosomal miR-205-3p downregulates AR, promoting epithelial–mesenchymal transition (EMT) and metastatic spread, while C/EBPβ-mediated activation of kinesin family member C1 (KIFC1) drives EMT and invasiveness in AR+ TNBC." (PMID 41383624, 2025). "Similar to FOXA1, overexpression of HOXB13 in an non-neoplastic prostate cell line pushed the AR cistrome to a more tumor-like profile." (PMID 40833121, 2025). "The proportion of PCa cell subsets with no or low expression of AR (AR−/low) in the tumor is related to the degree of malignancy." (PMID 39711287, 2025). "Matching our RNA-Seq results, PROX1 expression was increased in populations of cells in an AR activity–low tumor and was highly expressed in DNPC and NEPC tumors but not in ARPC." (PMID 40454483, 2025). "Moreover, the examination of gene expression and violin plots demonstrated a high expression of a group of AR signature genes, including KLK3, AR, TMPRSS2, NKX3.1, and AMACR across all clusters, indicating their tumor origin." (PMID 38732035, 2024). "The AR amino-terminal domain (NTD) has emerged as a target for novel inhibitors, with recent studies identifying compounds that exhibit anti-androgen activity and reduce tumor burden." (PMID 39796704, 2024). "The liver metastases and PDX tumor histology slides were negative for AR, PSA, PSAP and ERG protein expression; the tumor strongly expressed KRT7 and focally 34βE12." (PMID 38907236, 2024). "IHC AR and H&E staining was used to confirm whether the tumors in various organs originated from the AR-expressing 22Rv1-iRFP-GFP tumor metastasis." (PMID 38072969, 2024). "Comparison of AR status, similar to comparison of ER or HER2 status of MRD with tumor tissue (PT or metastatic lesion) can reveal differences and might contribute to selected patients for anti-androgen therapy." (PMID 37902839, 2024).
tumor (continued). "In addition to tumor cells, TME-resident macrophages and fibroblasts express AR and are therefore also affected by ADT." (PMID 38383542, 2024). "AU-24118 demonstrated tumor regression in a model of castration-resistant prostate cancer (CRPC) which was further enhanced with combination enzalutamide treatment, a standard of care androgen receptor (AR) antagonist used in CRPC patients." (PMID 38464081, 2024). "Inhibiting menin with MI-503 also reduces cell proliferation, colony formation, and tumor xenograft growth in AR-negative cell lines." (PMID 39336822, 2024). "Despite upregulation of select prostate luminal epithelial markers, canonical AR signaling was not significantly rescued in fNICD2-#1 luminal lineage tumor foci." (PMID 39024561, 2024). "While the reason for this male predominance remains unknown, one hypothesis is that the androgen receptor (AR) plays a critical role in DSRCT and elevated testosterone levels in males help drive tumor growth." (PMID 38575753, 2024). "The percent of AR-positive nuclei was higher in adjacent non-tumor but not tumor tissues from AA men compared to EA men (78.20% vs. 73.28%, P < 0.01)." (PMID 38566104, 2024). "Compared to normal hepatocytes from control tissue, the tumor cells were positive for nuclear AR (androgen receptor) expression but had no increased EZH2 (Enhancer of Zeste 2 Polycomb Repressive Complex 2 Subunit) protein expression." (PMID 39061609, 2024). "Furthermore, we provide the first evidence that silencing GATA3 in MDA-MB-453 cells enables AR to stimulate proliferation, supporting the concept that AR/GATA3 interactions are tumor suppressive even in this context." (PMID 38317241, 2024). "The knockdown of either PCGEM1 or PRNCR1 significantly inhibited in vivo tumor growth in a xenograft mouse model, but these proteins were not implicated in CRPC or AR signaling." (PMID 38339274, 2024). "The tumor-suppressing miR-143-3p exhibited a notable response to the lncRNA-SARCC and AR alterations, as it possesses AREs in its promoter region, indicating the involvement of the AR as a transcription factor that binds to suppress its activity." (PMID 39585048, 2024). "The PPI network analysis, informed by topological parameters, suggested that PIK3R1, SRC, AR, and MMP9 could be considered as key target genes for the combined anti‐tumor immunity effects of Danggui and Huangqi." (PMID 38863309, 2024). "Lathyrol and cisplatin inhibit the proliferation of RCC xenografts, reduce the protein expression levels of AR, CYP17A1, SPHK2, PARP1, E-cadherin, and ZO-1 in tumor tissues (P < 0.05), and promote the protein expression levels of N-cadherin, β-catenin, vimentin and α-SMA (P < 0.05)." (PMID 38965120, 2024). "By IHC, the tumor cells in this dural region were positive for AR (diffuse) and PD-L1 (patchy, tumor proportion score 5%) without significant reactivity to INSM1 and CHGA." (PMID 39349591, 2024). "Specifically, a subpopulation of poorly differentiated tumor cells with the cellular properties of lacking both nuclear AR and SYN expression, termed Solid-PCa, was identified in both primary and metastatic PCa lesions." (PMID 38336745, 2024). "Multiplex immunofluorescence in additional prostatectomy and patient tumor specimens further confirmed the KRT8+/AR+ normal epithelial cells to have no detectable expression of NSD2, which was robustly expressed in the transformed epithelial cells." (PMID 39251788, 2024). "Previously, we identified that tumor-suppressive miR-99b-5p is frequently downregulated in aggressive African American (AA) PCa and European American (EA) CRPC, leading to upregulation of mTOR, androgen receptor (AR), and HIF-1α signaling." (PMID 38792011, 2024).
tumor (continued). "Together, these data demonstrate that IST5-002 inhibits AR mRNA levels and CWR22Pc tumor growth in a non-castrate setting in vivo." (PMID 38416822, 2024). "AR signaling intersects with other pathways, such as PI3K/AKT and DNA damage repair mechanisms; thus, combination therapies might be able to overcome tumor resistance." (PMID 39335158, 2024). "While ALDH1A1 negatively correlates with AR target genes in noncancerous prostate epithelium, this mutual exclusivity reduces upon tumor development." (PMID 38169509, 2024). "The immunohistochemistry analysis of the breast mass revealed positive staining for ER, PR, HER-2, AR and Ki67 in the tumor cells, while negative staining was observed for P63, Calponin, CK5/6 and CK14." (PMID 38388422, 2024). "CXCR2-driven NE cells are critical for the tumor microenvironment by providing a survival niche for AR+ luminal cells; consequently, combination of CXCR2 inhibition and AR targeting effectively inhibited lineage plasticity and NE transition in mouse xenograft models." (PMID 39363904, 2024). "The inhibition of both AR and PI3K in LAR xenografts decreases tumor growth." (PMID 38339092, 2024). "Targeting a single molecule (e.g., AR) does not benefit all patients, and does not affect all tumor cells equally." (PMID 38887275, 2024). "AR was co-expressed in a subset of HR+ tumors and in a subset of HR−/HER2− tumor cells." (PMID 38167908, 2024). "Besides the cross-talk between HR and AR, there is also evidence of AR’s involvement in HER2 signaling pathways and its role in promoting tumor cell proliferation in HER2-positive BC." (PMID 39768587, 2024). "AR expression and nuclear localization was observed in tumor cells formed in male but not in female mice for both JN-DSRCT-1 and BER-DSRCT." (PMID 38575753, 2024). "Since KHSRP acetylation can respond to androgen stimuli or AR activity, we believe that KHSRP acetylation may play a critical regulatory role in the AR‐mediated DDR and is required for tumor growth in PCa." (PMID 38501452, 2024). "The atypical cyclin CCNG2 (Cyclin G2) acting as a tumor suppressor, is identified here as a novel downstream direct target gene of both BHLHE40 and AR by ChIP-seq and RNA-seq to mediate SAL-induced cellular senescence and linking clock genes with tumor suppression." (PMID 38902772, 2024). "Overall, 1508 showed AR-mediated tumor suppression; AR affected proliferation in Leo but not migration or invasion; and EMT and AR regulated migration and invasion in 1258 but not proliferation." (PMID 39201315, 2024). "Contrary to this, the expression of AR showed a positive impact on the DFI and a negative association with tumor grade." (PMID 38929666, 2024). "Importantly, T cell-intrinsic androgen receptor signaling functions to promote CD8 T cell exhaustion in tumor models, blunting male anti-tumor CD8 T cell activity." (PMID 38915570, 2024). "This trend was maintained between AR and HOXB13, although slightly reduced in tumor (normal prostate: r = 0.804, P = <0.0001; tumor: r = 0.598, P = 0.006), and between PSMA and AR (normal prostate: r = 0.878, P < 0.0001; tumor: r = 0.458, P = 0.048)." (PMID 38936974, 2024).
tumor (continued). "The tumor was diagnosed as b-HCA by standard immunostaining assays, which also showed expression of AR (androgen receptor) in the lesional cells, indicating receptor activation, but with no increase in EZH2 (Enhancer of Zeste 2 Polycomb Repressive Complex 2 Subunit) protein expression." (PMID 39061609, 2024). "On the other hand, since a negative-loop feedback regulation between two genes was well-reported to be involved in the regulation of tumor progression, we herein investigated whether PAX6 could also regulate the transcription of AR as feedback." (PMID 38745318, 2024). "In these studies, knocking down menin in AR-negative cells increases apoptosis and reduces cell proliferation and tumor xenograft growth." (PMID 39336822, 2024). "No specific staining was observed for AR, while tumor cells exhibited a strong nuclear positivity for SV40LT, demonstrating MS-pPC-193ST cells as origin of tumors." (PMID 38704600, 2024). "IHC performed on the patient biopsy and CP336/CP336c revealed that Ki67 was higher in the AR-negative/BCL2-positive tumor cell population." (PMID 39286979, 2024). "The expression of AR did not correlate with tumor size, pT stage, nodal status, Her2 status, and Ki67 labeling index." (PMID 39497884, 2024). "Consistently, combined NSD1 and NSD2 inhibition resulted in significant cytotoxicity in AR-positive PCa cells, whereas inactivation of either genes alone had little to no tumor-killing effect in prostatic cell lines." (PMID 39251788, 2024). "The anti-tumor effects of EZH2 inhibition may be through downregulation of cell-cycle related genes in PRAD and other AR-low NEPC-transitioning models, potentially collaborating with its impact on AR signaling." (PMID 38405800, 2024). "Conversely, AR can bind to the NXTAR promoter and inhibit AR expression using a small molecule inhibitor of ACK1/TNK2, thereby inhibiting the proliferation of enzalutamide-resistant cells and reducing enzalutamide resistance during tumor therapy." (PMID 39655078, 2024). "Based on the working current classification of advanced PCa, this tumor fits into a class of double-negative CRPC expressing neither AR or neuroendocrine features (personal communication PCF Pathology working group)." (PMID 38907236, 2024). "Immunohistochemical staining of the tumour recurrence was negative for AR expression but strongly HER2-positive (using the Ventana anti-HER2/neu (4B5) rabbit monoclonal primary antibody)." (PMID 39330047, 2024). "Notably, in both the AR+ (DU145) and AR- (PC3) IL30-expressing tumor models, treatment with CRISPR/Cas9gRNA-hIL30-loaded immunoliposomes substantially improved survival." (PMID 39232121, 2024). "AR has been related to promoting tumor proliferation when ERα is not expressed, as it has been studied that AR influences in PI3K/AKT pathways." (PMID 38338747, 2024). "Also, increased AR expression was positively correlated with HIF-2α and VEGF-A, thus enhancing the tumor cells’ invasion through hematogenous spread." (PMID 39585048, 2024). "Third, using VCaP cells, which were isolated from a CRPC tumor, and 1 hormone-naive ERα-positive PDO line, we showed that E2 could bypass AR signaling to promote proliferation, growth, and metabolism, even when the anti-androgen enzalutamide was present." (PMID 38625747, 2024). "Positive staining for pMET and nuclear β-catenin, with no nuclear AR staining was also detected in lung metastatic tumor cells." (PMID 38336745, 2024). "The results recapitulate findings from the Roswell Park cohort, where we observed an increase in AR transcriptional activity in tumor versus non-tumor in EA but not AA men." (PMID 38566104, 2024). "However, ERG showed an opposite function of enhancing AR-related pathways when PTEN, a phosphatase inhibiting the development of tumor by antagonizing the activity of phosphorylases, was lost." (PMID 38800374, 2024).